GRIA4 (glutamate ionotropic receptor AMPA type subunit 4)
Diseases named in the same sentence as GRIA4 in open-access papers (continued):
Sharing a sentence is not in itself a finding about the gene and the disease.
tumor (9 papers, 2012 to 2025). "Among these alterations, the CGI associated with GRIA4 (Glutamate Ionotropic Receptor AMPA Type Subunit 4) gene reached very high methylation levels in tumour samples compared with normal ones and it has been shown as an excellent putative biomarker but also potentially functionally involved in CRC." (PMID 34719006, 2022). "Methylation in GRIA4 is significantly higher in tumor tissue compared to its adjacent non-tumor tissue." (PMID 37476382, 2023). "On average, GRIA4 hypermethylation in primary tumor plasma was 2.8-fold higher (p=0.39), and in metastatic plasma, 16.4-fold higher (p=0.0011) compared to healthy individuals." (PMID 37476382, 2023). "In the current work, we focused on detecting hypermethylation status of gene GRIA4 in CRC patients using primary tumor/metastatic tissue and complementary pre- and post-surgical plasma samples." (PMID 37476382, 2023). "Our results showed significant GRIA4 hypermethylation increase in primary tumors and liver metastases compared to their adjacent non-tumor tissues (colon, rectum, or liver)." (PMID 37476382, 2023). "GRIA4 hypermethylation was, on average, 2.8 and 16.4 times higher in primary tumor and metastatic plasma than in healthy individuals." (PMID 37476382, 2023). "We showed that GRIA4 hypermethylation from the tumor was detectable in liquid biopsy plasma samples." (PMID 37476382, 2023). "GRIA4 methylation analysis of the investigation cohort confirmed a statistically significant hypermethylation (average ΔΔCt = − 2.33, p value < 0.0001) in tumoural samples compared to controls, being ΔCt inversely correlated to methylation levels." (PMID 34719006, 2022). "Despite aberrant promoter hypermethylation of ALDH1A2, OSR2, GATA4, and GRIA4 have already been reported in several human tumor cell lines or tumor tissues." (PMID 34745985, 2021). "GRIA4 showed hypermethylation in 6/10 tumour samples, while VIPR2 was hypermethylated in 7/10 tumour samples." (PMID 32599859, 2020). "Non-tumor tissue of primary tumor patients (colon/rectum), with average methylation of 14.02% (ranging from 2.09 to 24.92) (N=5) had almost five times higher GRIA4 methylation status compared to non-tumor tissue of metastatic patients (liver), ranging from 1.44% to 4.87% (average 2.93%), p= 0.012." (PMID 37476382, 2023). "Normal cell DNA methylation pattern varies along GRIA4 gene, with lower methylation values in the promoter region than in the gene body, while, in tumour samples, higher DNA methylation levels in the promoter region and lower in the gene body have been detected compared to controls." (PMID 34719006, 2022). "Of 22 differentially methylated promoters common between all LS tumor groups, seven inversely correlated with expression: ADHFE1, DAPP1, FBLIM1, GRIA4, HOXA3, KLF17, and ZNF528." (PMID 40753397, 2025). "The aim of our study was to develop sensitive droplet digital assay to examine GRIA4 methylation status in CRC patients, either with a primary tumor or with metastases." (PMID 37476382, 2023). "Concerning average beta values of GATA4, GRIA4, and IRX4, the patients with tumor stage IV had the highest level as compared to the subgroup patients with stage I/II/III tumor." (PMID 34745985, 2021). "A pan-cancer analysis with 10,967 tumor samples in 32 TCGA cohorts revealed that a low frequency of ALDH1A2 (1.4%), OSR2 (5%), GRIA4 (3%), GATA4 (4%), and IRX4 (5%) was genetically altered." (PMID 34745985, 2021). "This analysis confirmed the significant lower expression level of GRIA4 and VIPR2 in tumour tissues than in normal ones." (PMID 32599859, 2020). "In summary, our work was focused on the methylation and expression analyses of GRIA4, VIPR2, SPOCK1 and SLC6A3, belonging to gene families involved in the crosstalk between tumour cells and the environment." (PMID 32599859, 2020).
tumor (continued). "The current study confirmed GRIA4 methylation alteration in CRC and gives further support of its possible role in tumour by means of the altered expression detected at the RNA and protein level." (PMID 32599859, 2020). "We detected significantly increased GRIA4 methylation in tumor tissues compared to their adjacent non-tumor tissue, p<0.0001." (PMID 37476382, 2023). "The absence of hypermethylation of GRIA4 and VIPR2 associated CGIs in CRC tissue samples with low content of tumour cells highlights the high specificity of these two biomarkers for CRC detection." (PMID 32599859, 2020).
cancer (8 papers, 2014 to 2025). A tumor composed of atypical neoplastic, often pleomorphic cells that invade other tissues. "Several cancer-related methylated genes have been identified in CRC patients, including gene GRIA4, showing promising diagnostic potential." (PMID 37476382, 2023). "Based on our data, it can be inferred that GRIA4 serves as a tissue specific biomarker for the colon/rectum tissue, thus is suitable for cancer classification." (PMID 37476382, 2023). "VIPR2 was selected for its functional role and the involvement of vasoactive intestinal peptide receptors in cancer, while GRIA4 was chosen because it has previously shown methylation alterations in CRC tissues as well in plasma and stool samples." (PMID 32599859, 2020). "In contrast, GRIA4 is subject to DNA methylation and inhibition of GRIA4 expression increased cancer cell proliferation." (PMID 25326682, 2014). "Dysregulated signaling of GRIA4 may play a role in cancer development by affecting different signaling pathways involved in proliferation and growth." (PMID 36901898, 2023). "Although knockdown of GRIA4 has been associated with dysregulation of genes involved in invasion and metastasis, its functional role in cancer is not fully elucidated." (PMID 32599859, 2020). "The second set of three genes, GNAO1, GRIA4 and KCNA5, has been less researched, with only a few studies related to cancer." (PMID 30987631, 2019).
neurodevelopmental disorder (3 papers, 2021 to 2023). A behavioral and cognitive disorder with onset during the developmental period that involves impaired or aberrant development of intellectual, motor, or social functions. "Our patient is the sixth case of NEDSGA, in which neurodevelopmental disorders with seizures and abnormal gait were the most common phenotypes caused by pathogenic variants in GRIA4." (PMID 35518358, 2022). "NEDSGA is a newly recognized rare neurodevelopmental disorder caused by a heterozygous variant in the GRIA4 gene." (PMID 35518358, 2022).
genetic disorders (1 paper, 2022). "Our findings enriched the phenotypic spectrum of genetic disorders associated with GRIA4 variants." (PMID 35518358, 2022).
GRIA4 also shares sentences with these, for which no sentence is quoted: cognitive deficits (4 papers); amyloidosis (3); glioblastoma (3); psychiatric disorder (3); alcohol (2); Alzheimer disease (2); depression (2); mood disorder (2); neurodegenerative disease (2); nicotine dependence (2); rhabdomyosarcoma (2); abdominal aortic aneurysm (1); adenoma (1); anxiety disorder (1); atopic dermatitis (1); autism spectrum disorder (1); brain disorder (1); cerebellar ataxia (1); cognitive decline (1); cognitive disease (1); colon adenoma (1); cortical atrophy (1); dermatopathies (1); developmental delay (1); diabetic retinopathy (1); Dyskinesia (1); focal epilepsy (1); Gait ataxia (1); genetic generalized epilepsy (1); herpes zoster (1).
A further 8 diseases each share a sentence with GRIA4 in 1 paper.